MMP2 (matrix metallopeptidase 2)
Diseases named in the same sentence as MMP2 in open-access papers (continued):
Sharing a sentence is not in itself a finding about the gene and the disease.
prostate carcinoma (continued). "Two possible downstream effects were proposed for JUNB: the induction of p16 associated cell cycle arrest and the suppression of MMP2, which is involved in the progression of prostate cancer." (PMID 28005952, 2016). "MMP-9 and MMP-2 expression has been implicated in the development and progression of many tumors, such as bladder, colorectal, lung cancer and prostate cancer." (PMID 26742965, 2015). "HER-2 has been associated with castrate resistant prostate cancer and matrix metalloproteinase-2 (MMP-2) in the dissemination and invasion of tumor cells as well as activating angiogenesis." (PMID 23766685, 2013). "Matrix metalloproteinase-2 (MMP-2) expression in primary prostate cancer is associated with a worse prognosis." (PMID 23766685, 2013). "It has been reported that MMP-2 is one of targets of miR-29b in Hela cells and prostate cancer cells, so that we are interested in the association of miR-29a and MMP-2." (PMID 21573166, 2011). "Recently, MMP2 was also linked to an invasive phenotype of prostate cancer cells and expression of MMP2 in malignant prostatic epithelium was demonstrated to be an independent predictor of prostate cancer disease-free survival." (PMID 19956729, 2009). "MMP‐2 is an immunomodulator of cytoskeletal remodeling associated with tumor malignancy, invasiveness, and the ability to metastasize to distant organs that have been evidenced in prostate cancer for many years." (PMID 37644825, 2023). "Moreover, an interesting paper found that the expression of MMP2 in bone marrow micro-metastasis is associated with the presence of circulating prostate cells and a worse prognosis in prostate cancer patients treated with radical prostatectomy." (PMID 38255186, 2023). "However, the association between the rs243865 single-nucleotide polymorphisms in the matrix metalloproteinase 2 gene (MMP2) and the risk for prostate cancer is inconclusive." (PMID 29069837, 2017). "Therefore, fixed-effect model was used for pooling the association between MMP-2-1306 C/T polymorphism and risk of prostate cancer." (PMID 29249982, 2017). "Taken together, the MMP2 −1306C/T SNP is significantly associated with reduced risk of prostate cancer, and could be a candidate SNP for prostate cancer diagnosis." (PMID 29069837, 2017). "Overall and subgroup analyses of MMP-2-1306 C/T polymorphism and prostate cancer susceptibility." (PMID 29249982, 2017). "For example, although elevated expression of MMP9 and MMP2 is a marker of poor prognosis in prostate cancer, and linked to metastasis, their expression is from tumor-associated stroma cells and not from the cancerous epithelial cells, where the gene repositioning was detected." (PMID 27507988, 2016). "Moreover, highly metastatic variants of prostate cancers are revealed to contain relatively high levels of MMP-2 and MMP-9." (PMID 25563361, 2015). "Because cystatin C was down-regulated in prostate cancer tissues and associated with increased expression of MMP2 that is known to contribute to tumor invasion and metastasis, we wanted to investigate the role of cystatin C expression in prostate cancer cell growth, survival and invasion." (PMID 19956729, 2009). "Several natural compounds have demonstrated anti-cancer effects in NSCLC and prostate cancer through concurrent inhibition of MMP2 and MMP9 expressions." (PMID 40779492, 2025). "Prostate cancer (PCa) metastasis is reliant on the activity of proteases, such as matrix metalloproteinase-2 (MMP-2)." (PMID 41509368, 2025). "The activity of MMP9 and/or MMP2 proenzymes was increased in all representative stages of prostate cancer progression." (PMID 39796768, 2025). "Studies have shown that MMP2 is abnormally overexpressed in prostate cancer and plays a pivotal role in regulating prostate cancer metastasis." (PMID 40533843, 2025). "It promotes invasion in hepatocellular carcinoma and epithelial–mesenchymal transition (EMT) in prostate cancer via MMP-2, MMP-7, MMP-9, and NF-κB signaling." (PMID 39205642, 2024).
prostate carcinoma (continued). "Proteolysis of the extracellular matrix is required for prostate cancer cell migration and involves the secretion of proteolytic enzymes such as the matrix metalloproteinases (MMPs) MMP-2, 3, 7, 9, and cathepsins from late endosomes and lysosomes." (PMID 39796673, 2024). "The reduced activation of miR-146a was described in castration-resistant prostate cancer, where it controls the expression of EGFR and MMP2 in prostate cancer tissue." (PMID 37108432, 2023). "The resulting hydrolysate fractions were investigated for their antimicrobial and cytotoxic activities, including the expression of gelatinases mmp-2 and mmp-9 in human prostate cancer cell lines (PC3)." (PMID 37704667, 2023). "In prostate cancer, their roles have been discussed in a recent systematic-like review, where special emphasis is placed on MMP2, MMP7, and MMP9 since they are the most studied and most often positively correlated with prostate cancer tumorigenicity." (PMID 38255186, 2023). "The addition of SE to in vitro prostate cancer cells reduced MMP-2 and MMP-9 activity and the expression of nuclear transcription factor-kappa B, and increased TIMP-2 activity." (PMID 37623846, 2023). "In contrast, the downregulation of miR-130b in prostate cancer has been observed and overexpression of miR-130b can suppress tumor growth by downregulating MMP2." (PMID 35191803, 2022). "With regard to prostate cancer (PCa), MMP-2 rs243865 was significantly related to PCa incidence among the overall populations in the dominant model (OR = 1.365, 95% CI = 1.094–1.703, p = 0.006)." (PMID 35574300, 2022). "It is reported that THBS2 promotes bone metastasis of prostate cancer through inducing miR-376c-mediated MMP2 upregulation." (PMID 36195908, 2022). "Increased MMP2 transcript levels were also found to correlate the eHsp90 surface expression in primary prostate cancer samples." (PMID 36060252, 2022). "Extracellular Hsp90 has also been shown to promote cell motility in an ERK and MMP2-dependent manner and promote a mesenchymal phenotype in prostate cancer cells." (PMID 36060252, 2022). "Overexpression of FABP4 in prostate cancer results in the upregulation of MMP-2 and MMP-9, which promotes the invasion of cancer cells." (PMID 34685761, 2021). "Results showed that the MMP-2 transcript level in normal prostate epithelial cells from prostate cancer-containing tissue was significantly higher in the control group than in the genistein-treated group." (PMID 34336089, 2021). "Another allium derivative, diallyl disulfide (DADS), has been demonstrated to both decrease the expression and protein synthesis and inhibit the activity of MMP-2 and -9 in human prostate carcinoma LNCaP cells." (PMID 34572548, 2021). "In a prostate cancer model using Mmp2–/– mice, reduced liver metastasis and angiogenesis and increased survival was noted." (PMID 34032639, 2021). "Upregulation of SPOCK2 negatively regulated MMP2 gene expression, which in turn inhibited the invasion and metastasis of prostate cancer cells." (PMID 34987577, 2021). "Another study reported that exogenous expression of miR-29b regulates prostate cancer cell growth by modulating antiapoptotic and prometastatic ECM molecules, specifically by directly targeting and suppressing MMP2 in prostate cancer cells." (PMID 33809973, 2021). "In human prostate cancer cells, shikonin inhibited cell metastasis by reducing MMP2/MMP9 expression via AKT/mTOR and ROS/ERK1/2 pathways." (PMID 34812264, 2021). "Curcumin treatment caused a noteworthy reduction in MMP-2 and MMP-9 expression, in conjunction with reduced cellular invasion in vitro in prostate cancer cells (DU-145)." (PMID 34456716, 2021). "In this experiment, we proved that BWMT inhibited prostate cancer cell migration and invasion by reducing MMP-2/-9 protein expressions." (PMID 33958506, 2021).
prostate carcinoma (continued). "Taken together, these data demonstrated that PKM2 promoted tumor metastasis through upregulation of COX-2 and MMP2 to promote prostate cancer metastasis in vivo." (PMID 33117682, 2020). "In correlation, increased levels of MMP14 were detected in prostate cancer cells, and active MMP2 was found to be inversely correlated with the disease-free survival time in prostate cancer patients." (PMID 32575583, 2020). "miR146a has been shown to inhibit MMP2 expression in prostate cancer tissue 80 and the activity of MMP9 in human cardiac cells." (PMID 31183875, 2020). "Although a direct link between cystatin C and extracellular matrix protein MMP2 in prostate cancer has been suggested, a precise role of cystatin C in prostate cancer progression has not been established." (PMID 32180899, 2020). "It is reported that HSP27 can increase transforming growth factor b (TGF-b)-stimulated MMP2 activity and therefore promotes cell invasion in prostate cancer." (PMID 32200459, 2020). "For instance, we reported that the antimetastatic activity of SAM in breast and prostate cancer is likely due to downregulation of pro-metastatic genes, such as urokinase plasminogen activator (uPA) and Matrix metallopeptidase 2 (MMP2)." (PMID 32983966, 2020). "A previous study demonstrated that the CM of human MSCs (hMSCs) promoted the proliferation, migration, and invasion of PC-3 (prostate cancer cells) by upregulating of the expression of matrix metallopeptidase 2 (MMP-2) and matrix metallopeptidase 9 (MMP-9)." (PMID 31569731, 2019). "EGCG and gallic acid suppressed the invasion and migration of prostate cancer cells in correlation with reduced levels of MMP-2 and -9." (PMID 30823649, 2019). "Another study revealed that the knockdown of endothelial cell specific molecule-1 promoted tumorigenicity and metastasis through the regulation of MMP2/MMP9 in prostate cancer cells." (PMID 31777601, 2019). "MK2 and Hsp27 lead to activation of cell invasion and MMP-2 in prostate cancer, with past studies showing MAPK pathways to be activated during growth phase in bladder cancer cells." (PMID 30850014, 2019). "Short term treatment of US men with prostate cancer (PCa) with genistein decreases MMP-2 in prostate tissue." (PMID 30917169, 2019). "A subsequent study revealed that αvβ6 was required for TGFβ1-mediated MMP-2 expression in prostate cancer cells." (PMID 31438626, 2019). "αvβ6 has been shown to be expressed in prostate cancer bone metastases, and in vivo models of bone metastasis have shown that αvβ6 promotes osteolysis through upregulation of MMP-2 and parathyroid hormone-related protein." (PMID 31438626, 2019). "HSP90 can modulate the expression of fibronectin, as well as interact with matrix metalloproteinase 2 (MMP2) in prostate cancer and fibrosarcoma, respectively." (PMID 31752169, 2019). "Shikonin potently suppressed PC-3 and DU145 cell metastasis in a dose-dependent manner (0.5–2 μΜ) and inhibited the migration and invasion of the two aggressive prostate cancer cell lines by reducing MMP-2/-9 expression via AKT/mTOR and ROS/ERK1/2 pathways." (PMID 29495626, 2018). "Overexpression of MMP-2 was found in prostate cancer tissue, as compared with benign prostatic hyperplasia tissue, and the level of MMP-2 expression was correlated with clinical stage." (PMID 29949618, 2018). "In this study we sought to analyze to what extent variations in serum Zn level and polymorphisms in MT2A, MMP-1, MMP-2, MMP-7 and MMP-13 are related to prostate cancer among Polish men." (PMID 30036379, 2018). "We also determined if polymorphisms in several Zn-dependent genes (MT2A, MMP-1, MMP-2, MMP-7, MMP-13) contributed to prostate cancer risk." (PMID 30036379, 2018). "In a xenograft model of prostatic cancer, Curcumin treatment lead to a significant reduction of MMP-2 and MMP-9 expression, and the inhibition of the invasive ability of the tumor cells in vitro." (PMID 29890744, 2018).
prostate carcinoma (continued). "Curcumin-treated prostate cancer cells (DU-145) had significantly reduced MMP-2 and MMP-9, along with impaired in vitro cellular invasion." (PMID 29890744, 2018). "Numerous studies have indicated the crucial role of the MMP2 gene in the pathogenesis of the initiation, invasion, and metastasis of various tumors, such as ovarian cancer, hepatocellular carcinoma, prostate cancer, and lung cancer." (PMID 29069837, 2017). "The present meta-analysis, for the first time, comprehensively evaluated the associations between MMP-2-1306 C/T and MMP-1-1607 1G/2G polymorphisms and risk of prostate cancer." (PMID 29249982, 2017). "The aim of this meta-analysis was to shed some light on the genetic associations of MMP-2-1306 C/T and MMP-1-1607 1G/2G gene polymorphisms with prostate cancer susceptibility through incorporating all eligible studies." (PMID 29249982, 2017). "To explore the role of TSP-2/MMP-2 axis in bone metastasis of prostate cancer, we performed mouse models of bone metastasis by intratibial injection of cancer cells, and the bone metastasis was then detected by bioluminescence imaging." (PMID 28122633, 2017). "Background and Objective: Studies suggests that matrix metalloproteinase (MMP)-2-1306 C/T and MMP-1-1607 1G/2G polymorphisms affect the risk of prostate cancer." (PMID 29249982, 2017). "Many studies have examined the associations between MMP-2-1306 C/T (rs243865) and MMP-1-1607 1G/2G (rs1799750) polymorphisms and risk of prostate cancer." (PMID 29249982, 2017). "Curcumin was reported to inhibit the DNA-binding ability of ICN and suppress the MT1-MMP and MMP2 proteins in prostate cancer cells." (PMID 28977931, 2017). "Taken together, these results demonstrate that depleting RNase L leads to increased activity of MMP-2 and -9 in prostate cancer cells which correlates with increased cell migration." (PMID 28257035, 2017). "We showed that the expression level of SFMBT2 is critical for cell migration and invasion, which are fundamental features of prostate cancer malignancy through direct or indirect regulation of MMP-2, MMP-3, MMP-9, MMP-26, N-CoR, and KAI1 gene expression." (PMID 27340776, 2016). "Specifically, increased expression of MMP-2 and MMP-9 has been shown to be associated with prostate cancer progression and metastasis." (PMID 27340776, 2016). "Previous studies observed that reduced TGFα induced own-regulation of MMP-2 and exhibited low invasive ability in prostate cancer." (PMID 26843615, 2016). "Knockdown of LCN2 suppresses the invasion of prostate cancer cells through downregulation of MMP-2 and MMP-9." (PMID 25940797, 2015). "Silencing of filamin C increased the expression of matrix metallopeptidase 2 and improved the metastasis of prostate cancer in a zebrafish model." (PMID 25577646, 2015). "Previous studies revealed that CD147 plays an important role in the invasion and metastasis of prostate cancer by inducing matrix metalloproteinase 2 (MMP2) and MMP9 secretion." (PMID 25663928, 2015). "Further, genistein has been shown to decrease MMP-2 expression in human prostate cancer, coincident with its ability to inhibit human prostate cancer cell invasion." (PMID 25605009, 2015). "TIMP2 is a main negative regulator of MMP2 enzyme activity and is involved in several tumor metastasis processes, including prostate cancer." (PMID 24475196, 2014). "Although most of these studies were carried out in non-prostate cancer models, it is widely accepted that MMP-2 is important in the dissemination and invasion of various cancer cells and activation of angiogenesis." (PMID 24978435, 2014). "Accumulating evidence also suggests an enhancing effect of estrogens on prostate cancer progression through regulation of MMP-2 expression." (PMID 24978435, 2014). "In prostate cancer, HspB1 also appears as an important player that promotes EMT since its depletion is associated with decreased cell migration, invasion, and MMP-2 activity." (PMID 24514166, 2014).
prostate carcinoma (continued). "Among prostate cancer patients, those with metastatic disease had significantly higher plasma levels of MMP-2 and -9 than patients with localized disease." (PMID 24978435, 2014). "This overview summarizes findings on the tissue and blood expression of MMPs, their function, regulation and prognostic implication in human prostate cancer, with a focus on MMP-2, -7, -9, MT1-MMP and tissue inhibitor of metalloproteinase 1 (TIMP-1)." (PMID 24978435, 2014). "For instance, addition of fibronectin into common culture media induced high expression levels of pro and active forms of MMP-2 in several prostate cancer cell lines." (PMID 24978435, 2014). "Genistein, a phytoestrogen belonging to the family of isoflavones, inhibited cell invasion of prostate cancer cell lines by blocking MMP-2 activity." (PMID 24978435, 2014). "In prostate cancer cells, inhibition of p300 induced apoptosis via multiple pathways, and also decreased the expression of MMP-2 and MMP-9, which reduced the migratory and invasive ability of the cells." (PMID 25523932, 2014). "Activation of protease-activated receptor 1 (PAR1) and PAR2 by activating peptides increased expression of MMP-2 and -9 in prostate cancer cell lines." (PMID 24978435, 2014). "Many studies indicate that increased levels of MMP-2 or MMP-9 in the serum or tissue samples of prostate cancer patients are correlated with advanced stage." (PMID 24475196, 2014). "In prostate cancer, MMP-2 and -9 expression was regulated by the androgen receptor signaling pathway and was associated with tumor invasion." (PMID 24944688, 2014). "CDK11p58 inhibit the metastasis of AR positive prostate cancer cells through inhibition of integrin β3 and MMP2 in a kinase dependent manner." (PMID 24397471, 2014). "In particular, MMP-2 and MMP-9 have been implicated in the invasive potential of PC-3 prostate cancer cells." (PMID 25248616, 2014). "In prostate cancer, MMP-2 and MMP-9 expression indicate the tumor's invasive and metastatic potential." (PMID 25097794, 2014). "Not only Gal-3 expression levels but also its cleavage by matrix metalloprotease (MMP)-2/-9 are related to both breast and prostate cancers and are responsible for tumor growth, angiogenesis, and apoptosis resistance in mouse models." (PMID 24205440, 2013). "Similar to our results, some previous results also indicate that miR-29b suppresses growth of a human uterine carcinoma line (HeLa cells) and of prostate cancer cells by downregulating p85 alpha and MMP-2, respectively." (PMID 24147037, 2013). "In our study, we observed that miR-182 inhibitor decreased active-MMP-2 expression in prostate cancer cell lines as well as up-regulation of RECK protein." (PMID 23383207, 2013). "Gal-3 cleavage by matrix metalloprotease (MMP)-2/-9 is observed in breast and prostate cancers and is responsible for tumor growth, angiogenesis, and apoptosis resistance in mouse models and influence cell migration, angiogenesis, and tumor progression." (PMID 24205440, 2013). "We present an immunocytochemical study of the effect of androgen blockade on the expression of HER-2 and MMP-2 in bone marrow micrometastasis and the surrounding stromal cells in men with prostate cancer." (PMID 23766685, 2013). "We describe, for the first time in prostate cancer, that bone marrow stromal cells produce the opposite reaction, that of inhibition of MMP-2 expression." (PMID 23227342, 2012). "In prostate cancer, Emmprin knockdown by the siRNA led to migration and invasion through MMP-2, and MMP-9 expression." (PMID 22640183, 2012). "In men with bone scan positive prostate cancer the expression of MMP-2 is throughout the bone fragment and involves the surrounding stromal tissue." (PMID 23227342, 2012). "We present an immunocytochemical study of MMP-2 expression in circulating prostate cells (CPCs), disseminated tumor cells (DTCs), and micrometastasis (mM) in bone marrow of men with prostate cancer." (PMID 23227342, 2012).